IGF2BP3 (insulin like growth factor 2 mRNA binding protein 3)
Diseases named in the same sentence as IGF2BP3 in open-access papers (continued):
Sharing a sentence is not in itself a finding about the gene and the disease.
glioma (continued). "IGF2BP3 also stimulates glioma cell migration by enhancing the translation of p65 (RELA), a subunit of nuclear factor kappa-B (NF-κB) heterodimer, which can also in turn transcriptionally activates IGF2BP3 to form a feedback loop." (PMID 32244981, 2020). "A microarray analysis in glioma cells shows that IGF2BP3 mediates regulation of direct targets at transcriptome associated with cell cycle process, whereas direct targets at the translatome participating in apoptosis related pathways." (PMID 32244981, 2020). "The lower methylation levels of IGF2BP3 CpG sites may drive its overexpression, similar to mechanisms observed in gliomas." (PMID 39883704, 2025). "Additionally, IGF2BP3 is involved in the initiation of a circRNF10/ZBTB48/IGF2BP3 positive feedback loop in gliomas, leading to reduced Fe2+ accumulation and activation of ferroptosis defense mechanisms, which promotes glioblastoma (GBM) progression." (PMID 40271153, 2025). "Studies have also indicated that IGF2BP3 serves as a poor prognostic marker in gliomas." (PMID 40271153, 2025). "In addition, higher expression of IGF2BP3 is also correlated to lower overall survival rate in glioma/glioblastoma." (PMID 39198433, 2024). "Increased lipid peroxidation, elevated ROS levels, and ultrastructural modifications in mitochondria suggest that IGF2BP3 may play a critical role in regulating ferroptosis in glioma cells." (PMID 38429265, 2024). "Furthermore, IGF2BP3 knockdown glioma cells were incapable of forming tumors in a mouse xenograft model and were more susceptible to phagocytosis by microglia." (PMID 38429265, 2024). "Importantly, it was further confirmed that oHSV enhances NETosis in an IGF2BP3-dependent manner in primary cultured tumor cells and neutrophils obtained from glioma patients." (PMID 38167409, 2024). "Individual m6A RNA methylation regulators, including METTL3, ALKBH5, YTHDF2, and IGF2BP3, have been assessed in patient datasets to examine their expression levels across normal tissues, lower-grade gliomas, and glioblastomas, as well as their prognostic significance." (PMID 38398118, 2024). "We also observed that the promotion of glioma cell survival by IGF2BP3-induced NETosis in a contacted co-culture assay could be blocked by CSF3 neutralizing antibodies and enhanced by CSF3 recombinant protein." (PMID 38167409, 2024). "IGF2BP3 downregulated the expression of both m6A-associated writers (METTL3, METTL14) and erasers (FTO, ALKBH5), with a specific focus on FTO due to its more pronounced effect in both U87MG and GL261 glioma cell lines." (PMID 38167409, 2024). "Taken together, these findings suggest that IGF2BP3 knockdown induces ferroptosis in glioma cells." (PMID 38429265, 2024). "Additionally, IGF2BP3 knockdown-induced NETosis suppression and glioma cell survival was rescued by MIB1 overexpression." (PMID 38167409, 2024). "Furthermore, oHSV-induced NETosis in the contacted co-culture system promoted glioma cell survival in an IGF2BP3/CSF3-dependent manner." (PMID 38167409, 2024). "In this study, we demonstrated that depletion of IGF2BP3 induces ferroptosis in glioma." (PMID 38429265, 2024). "In addition, the overexpression of IGF2BP3 alone can increase the number of glioma cells, indicating that IGF2BP3 induces cancer cell survival both in a NET-dependent and a non-NET-dependent manner." (PMID 38167409, 2024). "Furthermore, the pan-cancer analysis demonstrated significant overexpression of IGF2BP3 in most cancer types, indicating its potential as a promising therapeutic target not only for glioma but also for other solid tumors." (PMID 38429265, 2024). "Furthermore, glioma cells become more sensitive to Taxol, temozolomide, and doxorubicin after the IGF2BP3 gene is knocked down, suggesting a role for IGF2BP3 in chemotherapy resistance." (PMID 38053093, 2023). "Both IGF2BP2 and IGF2BP3 are overexpressed in high-grade gliomas and indicate poor prognosis." (PMID 38072944, 2023).
glioma (continued). "Finally, we validated that IGF2BP3 protein expression was significantly higher in glioma than in normal tissue, especially in GBM." (PMID 36761737, 2023). "This study further confirmed the tumor-promoting role of IGF2BP3 in glioma." (PMID 37298373, 2023). "Moreover, IGF2BP3 showed higher levels in patients with GBM in comparison with other histological types of glioma." (PMID 36761737, 2023). "Furthermore, the expression of IGF2BP3 in different grades of glioma was detected by immunohistochemical staining and western blot." (PMID 36761737, 2023). "CircHIPK promotes glioma progression by regulating the miR-654/IGF2BP3 signaling pathway." (PMID 37964279, 2023). "In conclusion, IGF2BP3 acts as a tumor-promoting factor in glioma, and targeting its upstream regulators may be an approach to inhibit glioma progression." (PMID 37298373, 2023). "We confirmed a similar expression trend at the protein level, suggesting that IGF2BP3 may be a potential molecular biomarker for the diagnosis and prognosis of glioma, especially GBM, which is expected to be a new therapeutic target for glioma." (PMID 36761737, 2023). "IGF2BP3 may be a potential molecular biomarker for diagnosis and prognosis in pan-cancer, especially for glioma." (PMID 36761737, 2023). "Moreover, high expression level of IGF2BP1 and IGF2BP3 has been detected in many human cancers, including glioma and lung adenocarcinoma." (PMID 36761737, 2023). "Western blot analysis further verified the expression of IGF2BP3 protein in glioma." (PMID 36761737, 2023). "Assessment of IGF2BP3 in TCGA glioma samples also showed the same results." (PMID 35031058, 2022). "However, there is no report on the E3 ubiquitin ligase that mediates the ubiquitination of IGF2BP3 in glioma." (PMID 35031058, 2022). "Remarkably, IGF2BP3 participated in the maintenance and self-renewal of glioma stem cell (GSCs)." (PMID 36686749, 2022). "For instance, the high expression of circNEIL3 in glioma cells was found to block the binding between IGF2BP3 and HECTD4, via the modulation of protein ubiquitination and degradation, as well as cellular immunosuppressive responses, thereby promoting malignant progression of glioma." (PMID 36139074, 2022). "We then performed the CCK-8 cell proliferation assay to determine whether IGF2BP3 regulates the proliferation of GSCs, and glioma cell lines." (PMID 36686749, 2022). "For example, the expression of circHIPK3 in glioma tissue is markedly upregulated, and its high expression is observably to be correlated with the poor prognosis of the patients; circHIPK3 facilitates the proliferation and invasion of glioma cells by modulating IGF2BP3 expression." (PMID 36193069, 2022). "Additionally, IGF2BP3 knockdown significantly decreased the proliferation of glioma cells and promoted their apoptosis." (PMID 36686749, 2022). "Finally, circNEIL3 is packaged into exosomes by hnRNPA2B1 and transmitted to infiltrated tumour associated macrophages (TAMs), enabling them to acquire immunosuppressive properties by stabilizing IGF2BP3 and in turn promoting glioma progression." (PMID 35031058, 2022). "Our data demonstrated for the first time that IGF2BP3 could facilitate macrophages in the glioma TME and then reshape them to acquire an immunosuppressive phenotype." (PMID 35031058, 2022). "It was reported that high expression of IGF2BP3 in patients with glioma significantly reduced survival time, which was also associated with poor prognosis, suggesting that IGF2BP3 might be used as a potential prognostic biomarker for gliomas." (PMID 36118889, 2022). "GSEA of IGF2BP3 in TCGA glioma samples uncovered similar results, indicating that circNEIL3 may be involved in the regulation of TME cells." (PMID 35031058, 2022). "Thus, we sought to identify the E3 ligase involved in proteasome-mediated degradation of IGF2BP3 in glioma." (PMID 35031058, 2022).
glioma (continued). "In another study, circHIPK3 promoted glioma progression by regulating the miR-654/IGF2BP3 signaling pathway and could be used as a prognostic indicator of glioma." (PMID 33693013, 2021). "Moreover, glioma patients with a higher IGF2BP3 expression level had a shorter overall and disease-free survival, and IGF2BP3 expression was positively associated with glioma grades." (PMID 34657141, 2021). "The IGF2BP3 expression was found to increase as the tumor grade increased, indicating that IGF2BP3 might contribute to the progression of gliomas." (PMID 34721530, 2021). "The mutation map from cBioportal for Cancer Genomics further confirmed that the dysregulation of IGF2BP3 in patients with glioma was not related to somatic mutations." (PMID 34721530, 2021). "Results showed that IGF2BP3 loss led to the notable reduction of ZNRF3 level enriched by Ago2 antibody in U251 cells, suggesting that IGF2BP3 knockdown weakened the interaction of ZNRF3 and RISC in glioma cells." (PMID 34657141, 2021). "Based on the data presented, our study identified several m6A-related genes, especially IGF2BP3, that could be potential prognostic biomarkers of gliomas." (PMID 34721530, 2021). "IGF2BP3 promotes glioma cell migration by enhancing the translation of RELA/p65." (PMID 34212046, 2021). "As previous studies, IGF2BP3 facilitated viability and migration for glioma cells." (PMID 33634155, 2021). "The study unveiled the potential regulatory mechanism of IGF2BP3 in gliomas." (PMID 34721530, 2021). "The regulation of mRNA fate by IGF2BP3 in gliomas remains less well understood." (PMID 34721530, 2021). "In addition, HNRNPA2B1 could package circNEIL3 into exosomes and deliver it to infiltrating TAMs, thus enabling them to obtain immunosuppressive properties by stabilizing IGF2BP3, which in turn contributes to the progression of gliomas." (PMID 39268079, 2024). "Similarly, IGF2BP3 has been reported to promote glioma progression and migration." (PMID 38171932, 2023). "Moreover, it was reported that circNEIL3 could inhibit IGF2BP3 ubiquitination to promote glioma progression." (PMID 37407973, 2023). "Circ-HIPK3 may enhance IGF2BP3 expression in glioma cells by interacting with miR-654." (PMID 35883576, 2022). "In addition, hnRNPA2B1 could package circNEIL3 into exosomes and deliver them to infiltrating TAMs; circNEIL3 promoted the conversion of TAMs to an immunosuppressive phenotype by stabilizing IGF2BP3, which ultimately promoted glioma progression." (PMID 36497204, 2022). "Finally, circNEIL3 could be packaged into exosomes by hnRNPA2B1 and transmitted to infiltrating TAMs, thereby enabling them to acquire immunosuppressive properties by stabilizing IGF2BP3, in turn promoting glioma progression." (PMID 35031058, 2022). "Thus, further studies focusing on the regulatory mechanisms of IGF2BP3 in glioma could further our understanding of glioma carcinogenesis." (PMID 36686749, 2022). "Similarly, the DNA demethylation in the promoter region of IGF2BP3 could influence the progression of G-CIMP gliomas, and cg07166550/ALKBH5 could be used as prognostic biomarkers in prostate cancer." (PMID 33718187, 2021). "Moreover, we identified an important RBP IGF2BP3 during glioma progression." (PMID 32047515, 2019). "Another study revealed that the lncRNA WEE2-AS1 can be methylated by m6A and recognized by IGF2BP3, which activates the PI3K-AKT signalling pathway, leading to the occurrence of glioma." (PMID 40469294, 2025). "In gliomas, the expression levels of METTL3, ALKBH5, YTHDF2, and IGF2BP3 were found to be elevated compared to normal brain tissues." (PMID 38398118, 2024). "Overexpression of FTO effectively suppressed the IGF2BP3-induced upregulation of MIB1 and overall increase in m6A, inhibiting IGF2BP3-induced NETosis and glioma cell survival." (PMID 38167409, 2024). "In this work, we report that IGF2BP3 initiates a reciprocal regulation between MIB1 and FTO to drive m6A-mediated NET formation and glioma progression." (PMID 38167409, 2024).
glioma (continued). "As a result, we conclude that the overexpression of IGF2BP3 in glioma cells triggered NET formation, which contributes to the progression of glioma." (PMID 38167409, 2024). "While our study has advanced our understanding of the intricate interplay between IGF2BP3, GPX4, and ferroptosis regulation in glioma, it has also surfaced intriguing questions that warrant further exploration." (PMID 38429265, 2024). "We further revealed that the IGF2BP3/MIB1/FTO pathway forms a positive feedback loop in both T98G cells and primary cultured human glioma cells." (PMID 38167409, 2024). "In summary, our findings collectively demonstrate that IGF2BP3 plays a pivotal role in modulating GPX4 by directly interacting with GPX4 mRNA, thereby orchestrating the regulation of ferroptosis in glioma." (PMID 38429265, 2024). "In glioma models in female mice, a BET inhibitor enhances the oncolytic activity of oHSV by impeding IGF2BP3-induced NETosis, reinforcing virus replication through BRD4 recruitment with the CDK9/RPB-1 complex to HSV gene promoters." (PMID 38167409, 2024). "Recent studies have showed that IGF2BP3 played key roles in GBM maintenance and promoting the emergence of M2‐subtype macrophages, highlighting its vital roles on development of gliomas." (PMID 37309294, 2023). "However, the associated mechanisms of IGF2BP3 in gliomas have never been fully elucidated." (PMID 37309294, 2023). "The circNEIL3 stabilizes IGF2BP3 via blocking HECTD4-mediated ubiquitination, thereby promoting the oncogenic progression of glioma." (PMID 37968257, 2023). "Consistent with our results, circNEIL3 binds to IGF2BP3 and inhibits the ubiquitination of IGF2BP3 by E3 ubiquitin ligase HECTD4, thereby inhibiting the degradation of IGF2BP3 by the proteasome and promoting the proliferation and metastasis of glioma cells." (PMID 37340423, 2023). "Considering the important role of IGF2BP3 in gliomas, we further analyzed the role of IGF2BP3 in GBMLGG and identified significant correlations between IGF2BP3 expression levels and age, histological type and histological grade." (PMID 36761737, 2023). "EWSR1 promotes glioma progression by cyclizing circNEIL3, thereby blocking HECTD4-mediated ubiquitination, stabilizing IGF2BP3, and promoting glioma progression." (PMID 37964279, 2023). "IGF2BP3 target genes and the mechanisms by which IGF2BP3 contributes to oncogenesis can vary widely by cell type, from regulation of cell cycle-related genes in B-ALL and gliomas to migration and invasion genes in PDAC." (PMID 37760460, 2023). "We found that the expression of IGF2BP3 and RBM15B was increased in the glioma area compared to that in the para-tumor area." (PMID 35559019, 2022). "Thus, IGF2BP3 may play a significant role in the growth and development of glioma stem cells." (PMID 36686749, 2022). "GEPIA and Wang database analysis also showed a significant positive correlation between the expression of IGF2BP3 and WEE2-AS1 in glioma tissues." (PMID 36168628, 2022). "Thus, IGF2BP3 may act as a potent adjuvant for gene-targeted therapy in glioma." (PMID 36686749, 2022). "We found that the protein expression of IGF2BP3 and RBM15B was increased in the glioma tissue, while the expression of RBM15 was decreased compared to that in the para-tumor area." (PMID 35559019, 2022). "However, the mechanism of IGF2BP3 upregulation in glioma remains unclear." (PMID 35031058, 2022). "The expression of IGF2BP3, YAP1, CD68 (human macrophage marker) was enhanced in circNEIL3-high glioma tissues compared to circNEIL3-low tissues." (PMID 35031058, 2022). "The results showed that ANG, EXO1, FBXO17, IGF2BP3, and NSUN7 displayed distinctly higher expression levels in glioma compared to controls (p < 0.05)." (PMID 33634155, 2021). "After validation by RT-qPCR, IGF2BP3, NSUN7, EXO1, and FBXO17 had higher expression levels in glioma than controls." (PMID 33634155, 2021).
glioma (continued). "Our data confirmed the up-regulation of ANG, EXO1, FBXO17, IGF2BP3, and NSUN7 in glioma than normal samples (all p < 0.0001)." (PMID 33634155, 2021). "Based on the data presented, we proposed a vital role and potential regulatory mechanism of insulin-like growth factor 2 mRNA-binding protein 3 (IGF2BP3, also called IMP3) in gliomas." (PMID 34721530, 2021). "Indeed, our study demonstrated that BET inhibitors (JQ1, I-BET151) time-dependently inhibited the expression of both IGF2BP3 and CSF3 in glioma cells." (PMID 38167409, 2024). "Strikingly, IGF2BP3-KD U87 cells failed to form tumors and the IGF2BP3-KD group of mice exhibited significantly higher body weight compared to the control group, indicating a critical role of IGF2BP3 in glioma tumor formation." (PMID 38429265, 2024). "In gliomas, circNEIL3 could promote tumorigenesis by blocking HECD4-mediated IGF2BP3 ubiquitination." (PMID 38565547, 2024). "Additionally, IGF2BP3 showed a positive correlation with CD66b, MPO, and H3cit expression in glioma patients, indicating its potential role in NETosis induction." (PMID 38167409, 2024). "Collectively, our results confirmed that IGF2BP3/circGNB1/miR-515-5p/miR-582-3p/XPR1 axis could promote tumorigenesis and malignant progression of glioma via IL6/JAK2/STAT3 signaling pathway." (PMID 37407973, 2023). "Similarly, circ0046701 and circHIPK3 fostered proliferative and invasive features of glioma cells by targeting the axes miR-142-3p/ITGB8 (integrin subunit beta 8) and miR-654/IGF2BP3 (insulin-like growth factor 2 mRNA-binding protein 3), respectively." (PMID 35269953, 2022). "Overall, these data indicate that circ-HIPK3 promotes glioma progression by targeting miR-654 from IGF2BP3, implying that circ-HIPK3 may be a therapeutic target for glioma." (PMID 35883576, 2022). "Knockdown of IGF2BP3 attenuated GSC and glioma cell proliferation, invasion, and migration." (PMID 36686749, 2022). "Our data suggested that IGF2BP3, NSUN7, EXO1, and FBXO17 were highly expressed in AC-, MES-, NPC-, and OPC-like malignant cells, which could be related to poor prognosis for glioma patients." (PMID 33634155, 2021). "Zhang obtained mRNA transcription information and clinical data of gliomas from the TCGA database and found that the expression of RAB42, SHOX2, IGFBP2, HIST1H3G, and IGF2BP3 negatively correlated with 5-years OS; also, IGF2BP3 expression significantly positively correlated with glioma grades." (PMID 34721530, 2021). "IGF2BP3 also stimulates the migration of glioma cells by enhancing the translation of p65 (RELA), which is a subunit of the nuclear factor-kappa B (NF-κB) heterodimer, and p65 can also transcriptionally activate IGF2BP3 to form a feedback loop." (PMID 32943100, 2020). "Twenty-two vital RBPs, IGF2BP1, IGF2BP3, EIF4A3, hnRNPC, and AGO2, can bind to circRNAs and may play important biological functions in glioma." (PMID 33323543, 2020). "It is not yet clear how IGF2BP3 affects the immune microenvironment and whether it influences the response of gliomas to immunotherapy." (PMID 38167409, 2024). "Additionally, another member of the IGF2BP family, IGF2BP3, is similarly upregulated in glioma tissues compared to normal brain tissues, contributing to the invasive potential of glioma cells." (PMID 38398118, 2024). "Furthermore, multivariate Cox regression analysis indicated that high expression of YTHDC2 served as an independent positive prognostic factor for overall survival, while elevated expression of IGF2BP3 acted as an independent negative prognostic factor for the overall survival of glioma patients." (PMID 38398118, 2024). "Furthermore, we found that the protein level of IGF2BP3 was dramatically increased, while its level of ubiquitination was obviously decreased, in HECTD4-knockdown GBM cells, indicating that HECTD4 acts as an E3 ubiquitin ligase to degrade IGF2BP3 via the ubiquitin–proteasome pathway in glioma." (PMID 35031058, 2022).